SMIM5 (small integral membrane protein 5)
Synonyms: C17orf109; PP12104
Tractability: Antibody: UniProt predicts a signal peptide or a membrane-spanning region.
Gene: Protein-coding gene on chromosome 17 (75,628,368 to 75,642,570, forward strand). Ensembl gene ENSG00000204323.
Subcellular location: Membrane
Subcellular location (Human Protein Atlas): Vesicles; Golgi apparatus
Gene Ontology:
Molecular function: protein binding
Cellular component: membrane
Genetic constraint (gnomAD): Loss-of-function variants: 6 observed, 6.44 expected, observed/expected ratio (o/e) 0.93, 90% interval 0.5 to 1.72. That is too few expected variants to judge how well the gene tolerates losing a copy. Missense variants: 107 observed, 99.34 expected, observed/expected ratio (o/e) 1.08, 90% interval 0.92 to 1.26. Synonymous variants: 46 observed, 42.67 expected, observed/expected ratio (o/e) 1.08, 90% interval 0.85 to 1.38.
Homologues: Orthologues: chimpanzee SMIM5 (99% identical), macaque SMIM5 (97% identical), mouse Smim5 (78% identical), rat Smim5 (74% identical), pig SMIM5 (71% identical).
Diseases named in the same sentence as SMIM5 in open-access papers:
SMIM5 is named in the same sentence as 2 diseases in open-access papers, as found by Europe PMC text mining. Sharing a sentence is not in itself a finding about the gene and the disease. The quoted sentences say what the papers report.
mastitis (1 paper, 2020). Inflammation of breast tissue during lactation or postpartum due to an obstructed duct or infection. "The selection region on BTA 19 contains a gene encoding the small integral membrane protein 5 (SMIM5) that is associated with udder health and clinical mastitis in Holstein cattle." (PMID 33584805, 2020).
SMIM5 also shares sentences with these, for which no sentence is quoted: COVID-19 (1 paper).